ZNF891 (zinc finger protein 891)
Description:
May be involved in transcriptional regulation.
Tractability: PROTAC: ubiquitination databases record sites on it.
Gene: Protein-coding gene on chromosome 12 (133,104,779 to 133,130,289, reverse strand). Ensembl gene ENSG00000214029.
Subcellular location: Nucleus
Subcellular location (Human Protein Atlas): Nucleoplasm; Vesicles
Gene Ontology:
Molecular function: DNA-binding transcription factor activity, RNA polymerase II-specific; RNA polymerase II transcription regulatory region sequence-specific DNA binding
Biological process: regulation of transcription by RNA polymerase II; regulation of DNA-templated transcription
Cellular component: nucleus
Genetic constraint (gnomAD): Loss-of-function variants: 0 observed, 0.25 expected, observed/expected ratio (o/e) 0, 90% interval 0 to 1.87. That is too few expected variants to judge how well the gene tolerates losing a copy. Missense variants: 589 observed, 618.51 expected, observed/expected ratio (o/e) 0.95, 90% interval 0.89 to 1.02. Synonymous variants: 199 observed, 205.35 expected, observed/expected ratio (o/e) 0.97, 90% interval 0.86 to 1.09.
Homologues: Orthologues: chimpanzee ZNF891 (99% identical), macaque ZNF891 (92% identical), guinea pig ZNF891 (66% identical), pig ZNF891 (65% identical), mouse Zfp78 (31% identical), Drosophila melanogaster CG3281 (21% identical), Drosophila melanogaster CG2712 (19% identical), Drosophila melanogaster Phs (19% identical). Paralogues in human: ZNF558 (36% identical), ZNF778 (36% identical), ZNF25 (34% identical), ZNF557 (34% identical), ZNF266 (34% identical), ZFP37 (34% identical), ZNF177 (34% identical), ZFP90 (33% identical), ZNF805 (33% identical), ZNF264 (33% identical), ZNF77 (33% identical), ZNF554 (32% identical), and 50 more.
Diseases named in the same sentence as ZNF891 in open-access papers:
ZNF891 is named in the same sentence as 2 diseases in open-access papers, as found by Europe PMC text mining. Sharing a sentence is not in itself a finding about the gene and the disease.
ZNF891 shares sentences with these, for which no sentence is quoted: cancer (1 paper); tumor (1).